TEAD1 (TEA domain transcription factor 1)
Diseases named in the same sentence as TEAD1 in open-access papers (continued):
Sharing a sentence is not in itself a finding about the gene and the disease.
cardiac disease (4 papers, 2019 to 2024). "Understanding the regulatory mechanisms underlying Tead1 function in cardiomyocyte proliferation could allow identification of new targets for promoting cardiomyocyte proliferation for regenerative therapies for heart diseases in the future." (PMID 30811446, 2019). "Most frequently reported were TEAD1 (TEA Domain Transcription Factor 1) and PTPRN2 (Protein Tyrosine Phosphatase Receptor Type N2) in association with outcomes ranging from vascular to cardiac disease." (PMID 36991458, 2023). "Using gain- and loss-of-function genetic models, it was shown that the Hippo-YAP signaling pathway components Mst1/2, Sav1, Lats1/2, NF2, and downstream transcriptional regulators YAP and Tead1 regulate cardiac gene expression, cardiomyocyte proliferation, and cardiac disease status." (PMID 32938943, 2020).
cardiovascular disease (3 papers, 2018 to 2024). "TEA domain transcription factor 1 (TEAD1) is recognized as an important transcription factor that plays a key regulatory role in cardiovascular disease." (PMID 38225750, 2024).
kidney diseases (2 papers, 2024). "Among them were several genes known to be involved in kidney diseases, such as Kdm5a, Rb1, Tead1, Xbp1 and Ppargc1α with so far unknown role as sexual dimorphism regulators." (PMID 39278930, 2024).
peripheral neuropathy (1 paper, 2024). A disorder affecting the peripheral nervous system. "Tead1 cKO mice were smaller than WT mice at all ages, with labored breathing and widely splayed fore- and hindlimbs, indicative of severe peripheral neuropathy." (PMID 38456457, 2024). "Tead1 iKO mice appeared normal without obvious signs of peripheral neuropathy up to 5 months post-tamoxifen, the longest time of observation." (PMID 38456457, 2024).
TEAD1 also shares sentences with these, for which no sentence is quoted: cholangiocarcinoma (2 papers); cyst (2); embryonal rhabdomyosarcoma (2); genetic disease (2); acute kidney injury (1); adenoma (1); Anorexia (1); breast invasive carcinoma (1); cervical squamous cell carcinoma (1); clear cell renal cell carcinoma (1); coronary artery disease (1); diabetic retinopathy (1); dystrophin deficiency (1); esophageal squamous cell carcinoma (1); glaucoma (1); Hypertension (1); hypertrophy (1); intrahepatic cholangiocarcinoma (1); ischemic cardiomyopathies (1); Kaposi's sarcoma (1); laryngeal carcinoma (1); laryngeal squamous cell carcinoma (1); liver fibrosis (1); lung adenocarcinoma (1); lung squamous cell carcinoma (1); lymph node metastasis (1); medulloblastoma (1); metabolic dysfunction-associated steatotic liver disease (1); myeloid malignancies (1); myocardial ischemia (1).
A further 17 diseases each share a sentence with TEAD1 in 1 paper.